AKR1C2 (aldo-keto reductase family 1 member C2)
Diseases named in the same sentence as AKR1C2 in open-access papers (continued):
Sharing a sentence is not in itself a finding about the gene and the disease.
cancer (29 papers, 2010 to 2025). A tumor composed of atypical neoplastic, often pleomorphic cells that invade other tissues. "Given the association of AKR1C2 with oxidative stress mechanisms, the results also contribute to the broader understanding of how oxidative stress and detoxification pathways influence cancer development and progression." (PMID 39272833, 2024). "In this study, the suppression of ADH4, AKR1B10 and AKR1C2 genes and the subsequent encoded proteins may help to increase the intracellular methylglyoxal level which can subsequently lead to apoptosis in cancer cells." (PMID 27635343, 2016). "In chemoresistant cancers, their co-overexpression creates a robust antioxidant defense—AKR1C2 clears toxic aldehydes, while AKR1C3 sustains redox balance through GSH and survival pathways." (PMID 41009436, 2025). "AKR1C2 also metabolizes carcinogens and reduces ROS levels in cancer cells, thereby enhancing their tolerance to oxidative stress and drug stimuli and is abnormally expressed in various tumors." (PMID 40353060, 2025). "AKR1C2, -C3, and -B1 proteins were knocked down using two siRNAs, and AKR1C2 and -B1 knockdown significantly attenuated the viability of cancer cells after exposure to etoposide, doxorubicin, and daunorubicin compared with that of the negative control." (PMID 40361399, 2025). "A member of the human Aldo-keto reductases (AKRs) family, Aldo-keto reductase family 1 member C2 (AKR1C2), regulates steroid hormones and is aberrantly expressed in many cancers." (PMID 40531841, 2025). "It has been suggested that AKR1C2 is involved in steroid hormone biosynthesis and ROS formation, which can reduce the level of ROS in cancer cells, make them resistant to oxidative stress and drug stimulation and ultimately mitigate death." (PMID 40531841, 2025). "Individual oncogenes (oncogene lists obtained from MSigDB) with a high gain of novel isoforms in the Iso-seq cancer transcriptome were identified; for example, AKR1C2 and AKR1B10 are often overexpressed in HCC and contribute to hepatocarcinogenesis." (PMID 38185659, 2024). "Accordingly, several studies have also confirmed the important roles of aberrant AKR1C2 levels in the regulation of immune response in cancer patients." (PMID 36701414, 2023). "A study indicated that AKR1C2 expression is correlated with fat distribution of human bodies, and AKR1C2 plays a vital role in the process of some cancers." (PMID 36701414, 2023). "Cancer-related transcripts of AKR1C2, TPT1 and RPS27A were also down-regulated by AZD3355 in phHSCs." (PMID 34675338, 2021). "The aldo‐keto reductases family 1 member C2 (AKR1C2) has critical roles in the tumorigenesis and progression of malignant tumours." (PMID 32678482, 2020). "Several prior studies have also demonstrated similar findings regarding AKR1C2 in different cancers." (PMID 32678482, 2020). "Several studies reported that AKR1C2 has the prognostic values in some types of cancers." (PMID 36701414, 2023). "Recently, the significance of AKR1C2 in malignant tumors has been explored." (PMID 36701414, 2023). "Thus, levels of AKR1C1 and AKR1C2 gene expression are consistently overexpressed, in smoking-related cancer and upon smoke exposure." (PMID 28467356, 2017). "For example, AKR1C2 may facilitate cancer cell autophagy and apoptosis, and IFIT2 inhibits cell motility and invasiveness by EMT." (PMID 28881746, 2017). "Although the cytoprotective system is designed to prevent normal cells from becoming cancerous, in a cisplatin-induced ROS-rich environment, cancer cells may hijack the Keap1/Nrf2 system and induce AKR1C2 protein expression as an antioxidant substance." (PMID 24527071, 2014). "EAC exhibits the enhanced extracellular matrix remodeling (collagens, IGFBP7, PLAU) effects expected in an aggressive form of cancer, as well as evidence of reduced expression of genes associated with mucosal (MUC6, CA2, TFF1) and xenobiotic (AKR1C2, AKR1B10) defenses." (PMID 21829465, 2011).
cancer (continued). "However, previous findings on the exact significance of AKR1C2 have been inconsistent and highly debatable, we even don't know whether to regard it as a promoter or suppresser of cancers, and how it participates in the pathogenesis and development of ESCC have not been fully investigated." (PMID 32678482, 2020). "Among these, sulfotransferases (SULT1A1, SULT1A2, SULT1A3) and aldo-keto reductases (AKR1C1, AKR1C2, AKR1C3) were shown to contribute to disease progression and/or represent therapeutic targets in hormone-dependent forms of cancer, including EOC." (PMID 26372729, 2015). "Consistent with a role for NFE2L2 in vitamin D-mediated cancer prevention, a number of NFE2L2 target genes were increased in RWPE1 cells after 1,25(OH)2D treatment, e.g. GPX3, HMOX1, AKR1C2, and TXNRD1." (PMID 20070897, 2010). "Furthermore, AKR1C2, AKR1C3, and AKR1B1 knockdown attenuated the proliferation and invasive ability of cancer cells." (PMID 40361399, 2025). "Moreover, three members of aldo-keto reductases (AKRs), AKR1C1, AKR1C2, and AKR1C3, are overexpressed in cancer." (PMID 25243088, 2014).
neurological diseases (1 paper, 2025). "However, studies on the role of AKR1C2 in neurological diseases are limited." (PMID 40353060, 2025).
AKR1C2 also shares sentences with these, for which no sentence is quoted: parasitemia (3 papers); endometriosis (2); leukemia (2); adenoma (1); brain glioma (1); breast adenocarcinoma (1); diabetic macular edema (1); dilated cardiomyopathy (1); epilepsy (1); esophageal cancer (1); gynecological cancers (1); gynecological tumor (1); hypospadias (1); hypotension (1); idiopathic cardiomyopathy (1); ischemic cardiomyopathy (1); malaria (1); metastasis (1); Obesity (1); oesophageal adenocarcinoma (1); osteoporosis (1); pancreatic cancer (1); sarcopenia (1); schizophrenia (1); sex development disorder (1); Simpson-Golabi-Behmel syndrome (1).